INS (insulin)
Diseases named in the same sentence as INS in open-access papers (continued):
Sharing a sentence is not in itself a finding about the gene and the disease.
Obesity (continued). "In the hyperinsulinemic state (as commonly occurs with obesity), higher insulin levels in the portal circulation in response to hyperglycemia upregulate the growth hormone receptor (GHR) and augment GHR signaling, increasing hepatic IGF-1 production." (PMID 24280167, 2013). "It mediates impaired insulin action in obesity while facilitating increased glucose uptake and its utilization during exercise through a mechanism involving GLUT4." (PMID 23431467, 2013). "Here, we have demonstrated that removal of subcutaneous adipose tissue can be detrimental because obesity-induced increases in portal insulin and leptin concentrations following removal are exacerbated in mice that underwent this procedure." (PMID 23914298, 2013). "Previous studies have found contradictory associations between FABP2 genotypes and the occurrence of T2DM, obesity or decreased insulin sensitivity." (PMID 24156506, 2013). "Lower ghrelin concentration in obesity have attributed to higher insulin concentration, also lower ghrelin levels after eating attributed to increased insulin levels after carbohydrate intake in some studies." (PMID 24354802, 2013). "Obesity, sedentary lifestyle and high fat calorie perpetuate this cycle by lowering HSPs and thus, leading to metabolic inflammation and impairment of insulin signaling." (PMID 23894433, 2013). "Double knockout mice (p21-/-; p27-/-) developed hypercholesterolemia, glucose intolerance, and insulin insensitivity, which are metabolic adaptations of obesity." (PMID 23355973, 2013). "Correlation coefficients of nocturnal respiratory registration data with obesity indexes, insulin sensitivity and fasting glucose in 98 obese women." (PMID 23613841, 2013). "Due in part to the rise of obesity in the domestic cats, there is increasing literature on the effects of obesity and insulin sensitivity on gene expression in the domestic cat." (PMID 24312255, 2013). "The origin and roles of some novel adipokines in inflammation and insulin signaling and their responses to obesity, insulin resistance and bariatric surgery." (PMID 23772224, 2013). "Short-term exposure to FFA increases GSIS which results in increased insulin secretion following a mixed meal and enables storage of excess calories as fat which contributes to overweight and obesity." (PMID 23542897, 2013). "RG ameliorates metabolic syndrome by improving the insulin sensitivity of peripheral tissue, and enhancing the serum lipid profile, inhibiting obesity, and so on." (PMID 24177708, 2013). "Notwithstanding, other studies have reported that this polymorphism is not individually associated with basal metabolic rate, metabolic syndrome, BMI, obesity, insulin secretion or T2DM." (PMID 23365654, 2013). "In similar modeling, attenuation obtained by adding fasting insulin, instead of these markers, was only slightly more pronounced HR[obesity]=2.7, 95%CI 1.7–4.1; and HR[waist]=3.6, 95%CI 2.3–5.8)." (PMID 23806173, 2013). "The study showed that low 25(OH)D levels were associated with obesity (r=-0.35, p<0.01), increased plasma glucose levels after OGTT (r=-0.31, p<0.01) and decreased insulin sensitivity index (r=-0.28, p<0.01)." (PMID 23924693, 2013). "Both TCF7L2 and KCNQ1 have been shown to play essential roles in beta cell survival and function, and they have been suggested to be involved in the modulation of insulin sensitivity and obesity." (PMID 23990951, 2013). "In contrast, the expression of adiponectin, the adipocyte-derived adipokine with potent function in regulating insulin sensitivity, is downregulated during obesity." (PMID 23390531, 2013). "Earlier studies, using HOMA1 were in agreement with our findings for obesity and insulin metabolism." (PMID 31667005, 2013). "In support of the potentially protective role of S1P in obesity, endurance trained humans, who are remarkably insulin sensitive, have been shown to have ∼40% higher plasma S1P concentrations than untrained controls." (PMID 24039766, 2013).
Obesity (continued). "After administration of recombinant OC, insulin secretion increases, blood glucose decreases, and experimental obesity is attenuated." (PMID 23983685, 2013). "Similar results were observed when waist circumference and fasting insulin were considered in the models instead of obesity." (PMID 23806173, 2013). "The increased expression of TNFα in adipose tissue was considered to be responsible for the development of obesity or diabetes due to the induction of insulin resistance through downregulation of insulin receptors and glucose transporters." (PMID 23819063, 2013). "In the obesity, insulin sensitivity, bone density, and depression studies a total number of 333, 94, 273, and 228 subjects, respectively, completed the intervention period and had complete data sets." (PMID 23577264, 2013). "In the general non-diabetic population, circulating PEDF has been related to aspects of the metabolic syndrome, including obesity, triglyceride levels, diastolic blood pressure, glucose, and insulin levels." (PMID 23941060, 2013). "FGF21 has relatively recently been described to act as a hormone and protect from obesity, increase fat utilization and energy expenditure and improve insulin sensitivity." (PMID 23363332, 2013). "Earlier studies have shown that chemical-induced systemic HO-1 overexpression inhibits obesity and improves insulin sensitivity in diabetic animals." (PMID 23390531, 2013). "As central administration of IL-6 enhances energy expenditure and decreases obesity, IL-6 can also influence obesity and insulin sensitivity through a central nervous system mechanism." (PMID 23781214, 2013). "Despite this discrepancy regarding the levels of citrate, alterations of citrate levels suggest the disturbances in insulin or glucose levels in obesity." (PMID 24098417, 2013). "Beta cell physiology should be preserved throughout life but is adversely impacted with aging and altered metabolic states such as obesity that requires a sustained increase in insulin." (PMID 23542897, 2013). "The interaction between KSR2 and AMPK has been suggested to underpin some of the abnormalities of energy homeostasis and metabolism seen in Ksr2−/− mice, which include obesity, high insulin levels, and impaired glucose tolerance." (PMID 24209692, 2013). "Precocious adrenarche occurs in 15-30% of patients and is felt to be secondary to obesity or possibly increased adrenal exposure to insulin or IGF-1." (PMID 23962041, 2013). "IL-15-deficient mice become obese despite unaltered food consumption; IL-15 injections reversed both this obesity and diet-induced obesity, lowered glucose levels and increased insulin sensitivity." (PMID 23690769, 2013). "On the other hand, high insulin levels over a long period of time results in increased rate of obesity, hyperlipidemia, and hypertension." (PMID 23819128, 2013). "Estradiol substitution increases insulin sensitivity yields favorable changes in plasma lipid levels and by its anti-obesity effect decreases the accumulation of visceral fat deposition." (PMID 23061769, 2013). "The first involved matching weight-reduced women with normal-weight (BMI <25.0 kg/m2) controls to determine if obesity propensity affected insulin sensitivity." (PMID 23298367, 2013). "Four main systems have been identified as potential producers of cancer in obesity: insulin, insulin-like growth factor-I, sex steroids, and adipokines." (PMID 24073332, 2013). "Studies from two different laboratories have shown PTP1B-knockout mice exhibit enhanced insulin sensitivity, improved glucose tolerance and resistance to diet-induced obesity." (PMID 24366088, 2013). "We analyzed Munc18c gene expression in human visceral (VAT) and subcutaneous (SAT) adipose tissue and its relationship with obesity and insulin." (PMID 23700440, 2013).
Obesity (continued). "It is hence possible that circulating, distinct from adipose-derived, factors such as free fatty acids or insulin are also crucial in mediating the pro-tumorigenic effect of obesity and high fat diet (HFD)." (PMID 23560112, 2013). "IL-6 appears to play a dual role in skeletal muscle by mediating impaired insulin action in obesity and facilitating increased fuel metabolism during exercise." (PMID 23431467, 2013). "GPR40 is thought to contribute to obesity-induce hyperinsulinemia as it is required for FFA-stimulated insulin secretion." (PMID 23776696, 2013). "The increased production and release of free fatty acids is described in human and animal models of obesity as a consequence of insulin resistance." (PMID 24065093, 2013). "It is well documented that excessive energy supply and subsequent overweight and/or obesity adversely affect insulin action." (PMID 24348155, 2013). "For instance, the QTL for DFI on SSC 1 was homologous with HSA 6q23–24 region which has been found to significantly affect obesity-related traits in humans such as waist circumference, body mass index or fasting glucose and insulin levels in different studies." (PMID 23977060, 2013). "g. obesity, nutritional behavior, physical activity, mode of insulin therapy, compliance with and adherence to therapeutic recommendations." (PMID 23937662, 2013). "Ursolic acid is a very potent anti-inflammatory and insulin sensitizing agent with reported activities against the effects of obesity, such as the ability to counteract NF-κB, COX-2, and Akt activity." (PMID 23967401, 2013). "The present MeS model only develops mild hypertension and more than three other signs of MeS; obesity, impaired fasting glucose and high levels of insulin." (PMID 24250786, 2013). "Studies have shown that ER stress is reversed by Osteocalcin through nuclear factor-kappaB signaling, so impaired insulin sensitivity resulted from diet-Induced obesity improves." (PMID 24032041, 2013). "We show that elevations in plasma S1P are a feature of both human and rodent obesity and correlate with metabolic abnormalities such as adiposity and insulin resistance." (PMID 24039766, 2013). "Its major clinical benefit in obesity is preventing caloric intake, thus, reducing circulating lipid levels and improving insulin sensitivity." (PMID 23573093, 2013). "Similar elevation was also found in the pancreas islets of type 2 diabetic rats, while other observation declared a reduction of PGC-1α in the adipose tissue of insulin-resistant and obesity individuals." (PMID 24381715, 2013). "Obesity is typically accompanied by elevated circulating levels of insulin, bioavailable IGF-1 and leptin, as well as a series of pro-inflammatory cytokines." (PMID 23880059, 2013). "It becomes hyperphagic, hyperinsulinemic, and insulin resistant early in life (within 2 weeks of age), then develops obesity at the age of 3 to 4 weeks." (PMID 23671868, 2013). "The rats develop a distinct metabolic PCOS phenotype and suffer from obesity that is accompanied by enlarged adipocytes and insulin resistance." (PMID 23690868, 2013). "Metabolic dysfunction with obesity and insulin as well as leptin resistance can be observed in genetic models of HD expressing human full-length htt, such as the YAC and BACHD mice." (PMID 24376631, 2013). "Coincident with obesity, Ugcgf/f//CamKCreERT2 mice were less glucose tolerant than Ugcgf/f mice 12 wk p.i. and insulin sensitivity was marginally impaired 10 wk p.i.." (PMID 23554574, 2013). "These animals show normal insulin and glucose tolerance but are highly resistant to weight gain on a high fat diet, exhibiting no increase in serum lipids, insulin, or glucose levels and enhanced insulin-signaling under obesity inducing conditions." (PMID 23762820, 2013). "Compared with control group, both andronate-treated groups exhibited obesity with higher insulin concentrations (P < 0.05) but similar blood glucose concentrations." (PMID 22276997, 2012).
Obesity (continued). "During obesity, when resistance of adipose tissue to insulin develops (partly because of hypoxia generated following adipocyte hypertrophia/hyperplasia), enhanced lipolysis leads to a massive increase in plasma free fatty acids." (PMID 23201837, 2012). "Insulin and leptin are secreted into circulation in proportion to adipose tissue indicative of obesity in HFGP males." (PMID 22988521, 2012). "Neonatal MSG treatment is a model of obesity in rodents which causes alterations in hypothalamic arcuate nucleus (ARC) and impairs leptin and insulin signaling in this region resulting in hyperleptinemia and hyperinsulinemia." (PMID 23216967, 2012). "The mir-143 has recently emerged as an obesity-induced miRNA that inhibits INS-stimulated Akt activation and impairs glucose metabolism." (PMID 21977024, 2012). "This gene encodes for a protein implicated in regulating the unfolded protein response, which secondary to obesity impairs glucose homeostasis and insulin actions." (PMID 22607048, 2012). "Potential mechanisms linking obesity and thyroid cancer risk include elevated TSH levels, insulin resistance, and adipokines effect." (PMID 22778714, 2012). "In summary, the ATCC protected against development of diet-induced obesity, lowered blood insulin levels and appeared to affect liver steatosis in hypercholesterolemic mice on a high-fat diet." (PMID 23056479, 2012). "In order to determine which dietary regime results in the most appropriate mouse model for studies on obesity, glucose intolerance and islet adaptation to insulin resistance, the diets need to be evaluated in head to head comparisons." (PMID 23201760, 2012). "To determine a role of GPR26 in regulating obesity-related metabolic complications, we next analyzed changes in serum levels of insulin, ghrelin, adiponectin, and lipids in GPR26−/− mice on a high-fat diet." (PMID 22815809, 2012). "Since the discovery of adipose tissue inflammation in obesity and its impact on systemic insulin sensitivity, numerous studies have examined immune responses in fat depots in obese rodents and humans." (PMID 22313574, 2012). "Many studies have revealed that increased inflammatory response in hypothalamus produces insulin and leptin resistance contributing to the defective food intake both in genetic or dietary fat-induced obesity." (PMID 22844271, 2012). "Skeletal muscle resistance to the key metabolic hormones, leptin and insulin, is an early defect in obesity." (PMID 23115649, 2012). "Here we show that kinin B1R in adipocytes contribute to the regulation of systemic insulin sensitivity and predisposition to HFD-induced obesity." (PMID 23024762, 2012). "It is therefore possible that insulin and leptin promote eNOS synthesis and NO production early in obesity, but over time, the effect of the reactive oxygen species prevails." (PMID 22505944, 2012). "The reason for this is that smoking and obesity enhance the oxidative stress which results in decreased insulin secretion from pancreatic β-cell and decreased uptake of blood glucose into the muscle cells." (PMID 22520940, 2012). "The term “metabolically benign obesity” describes persons with elevated body mass and normal insulin sensitivity." (PMID 22768041, 2012). "On the other hand, adiponectin, another adipohormone secreted also by adipocytes, is present in low concentration in obesity-insulin resistant states." (PMID 22649556, 2012). "A cell-autonomous mechanism that involves the negative regulation of IRS1 function by serine phosphorylation was implicated in the regulation of insulin resistance induced by JNK1 and possibly by IKKβ during obesity." (PMID 23316186, 2012). "In obese and non-obese subjects, fasting concentration of BCAA correlates with obesity and serum insulin." (PMID 23088297, 2012).
Obesity (continued). "Thus, proper insulin action at the level of the adipose tissue is thought to be required for normal metabolic homeostasis, which include the regulation of whole body insulin sensitivity, the susceptibility to obesity, and the relationship between plasma leptin and body weight." (PMID 23024762, 2012). "IL-15 deficient mice become obese despite unaltered food consumption; IL-15 injection reversed both this obesity and diet-induced obesity, lowered glucose levels, and increased insulin sensitivity." (PMID 22935594, 2012). "In this paper we discuss the etiology and pathogenesis of nonalcoholic steatohepatitis with special focus on obesity, role of insulin resistance, and molecular mechanisms of hepatotoxicity." (PMID 22792473, 2012). "Obesity increases oxidative stress, estrogen and leptin levels, inflammatory responses, energy availability, and insulin insensitivity, while decreasing adiponectin." (PMID 22257467, 2012). "Increased infiltration of immune cells like macrophages into adipose tissue was observed in human and animal obesity and was reported to diminish local and systemic insulin sensitivity." (PMID 23284633, 2012). "Our results demonstrate that reducing the levels and activities of p/CIP and SRC-1 results in increased insulin sensitivity and resistance to obesity." (PMID 22859932, 2012). "In contrast, although GIP Tg mice demonstrated enhanced β-cell function, resulting in improved glucose tolerance and insulin sensitivity, they exhibited reduced diet-induced obesity." (PMID 22802954, 2012). "Insulin seems to play a key role, since amniotic fluid insulin levels during the third trimester correlate independently with infants' obesity." (PMID 23227034, 2012). "One key feature of obesity is the development of insulin and leptin resistance, resulting in an elevation of the circulating levels of these two hormones as a consequence of compensatory physiological responses to insulin and leptin insensitivity." (PMID 21904565, 2012). "The finding that myostatin knock-out mice are protected against obesity-induced insulin resistance as measured by a hyperinsulemeamic clamp suggests an effect of myostatin on insulin-mediated glucose uptake." (PMID 22615949, 2012). "This target body weight was selected because it has been shown to be a period of established obesity, adipose tissue inflammation, and insulin resistance in male mice." (PMID 22778716, 2012). "A 95 EEAI increased the expression of genes involved in lipid catabolism, enhanced fatty acid oxidation and insulin-stimulated glucose uptake in vivo as well as in human skeletal muscle cells, protected against diet-induced obesity." (PMID 22479450, 2012). "The specific aim of this study was to create a zebrafish obesity model by over expressing the insulin signaling hub of the Akt1 gene." (PMID 22623957, 2012). "A rat model of PCOS was successfully established with features of polycystic ovaries, obesity, irregular cycles of vaginal smear, increased plasma insulin levels, decreased insulin sensitivity, hyperandrogenism, and increased LH concentrations." (PMID 22276997, 2012). "These novel findings offer a common mechanism of FLD pathogenesis in states of both inadequate (prolonged fasting) and ineffective (obesity) insulin signaling." (PMID 22745692, 2012). "Unfortunately, plasma insulin and obesity-related parameters, such as leptin and tumor necrosis factor (TNF) α, were not measured in the earlier studies." (PMID 22748134, 2012). "Hormones such as leptin, amylin, GIP, and insulin, to which a suggested state of resistance is observed in obesity and T2D tend to decrease, favor a restored homeostasis." (PMID 22619730, 2012). "Obesity leads to increased ER stress in insulin-responsive tissues, but the precise contribution of ER stress to metabolic regulation, and modulation of ER stress by PTP1B requires additional investigation." (PMID 22509299, 2012).